TNF (tumor necrosis factor)
Diseases named in the same sentence as TNF in open-access papers (continued):
Sharing a sentence is not in itself a finding about the gene and the disease.
heart failure (continued). "For example, TNFα inhibitors are contraindicated in patients with heart failure NYHA class III-IV, multiple sclerosis and severe infections." (PMID 39336506, 2024). "Following immune dysregulation in heart failure, inflammatory cells in the body release inflammatory cytokines (such as TNF-α, IL-6, NF-κB), which drive the progression and worsening of heart failure." (PMID 39199348, 2024). "Post-marketing data with TNF-α inhibitors describe congestive heart failure or worsening existing heart failure after TNF-α inhibitor use, and it has also been reported to be associated with hypersensitivity myocarditis." (PMID 38785743, 2024). "Pignatelli and colleagues have documented a correlation between platelet activation and the plasma level of TNF- α among patients with heart failure in comparison with a control group." (PMID 38921252, 2024). "This is attributed to the release of various cytokines, such as IL-1α, IL-1β, IL-6, and TNF-α, which negatively affect myocardial healing and contribute to the development of heart failure." (PMID 38667586, 2024). "TNFα has been closely studied in heart failure before, and was suggested to be one of the mediators of systemic inflammation in HFpEF." (PMID 39311911, 2024). "Elevations in pro-inflammatory indicators like NF-kB and TNF-α—along with the activation of oxidative stress in myocardial injuries—result in apoptosis and heart contractile dysfunction, occasionally leading to cardiac failure." (PMID 39598433, 2024). "In all CHF patients, higher TNF, IL-10, SOCS1 and SOCS3 gene expression was associated with severity of heart failure according to MR-proANP (r = 0.4, p < 0.03, r = 0.39, p < 0.03, r = 0.45, p < 0.03 and r = 0.45, p < 0.02, respectively)." (PMID 38337428, 2024). "Patients with chronic conditions, such as kidney or heart failure, often exhibit elevated levels of TNF-α and its soluble receptors in their bloodstream." (PMID 38732255, 2024). "IL-10 can also reduce proinflammatory cytokines such as TNF-α, IL-1β, and IL-6, as well as cardiac contractility in heart failure." (PMID 39200761, 2024). "Increased values have been reported in heart failure, but also in infarcted myocardial tissue, with TNF-α having the role of stimulating the proliferation and expression of fibronectin at the level of fibroblasts in the injured myocardium." (PMID 39062865, 2024). "Another important factor involved in RVH and heart failure development is inflammation due to increases in the levels of interleukin (IL)-6, IL-1β, tumor necrosis factor-a (TNF-α), and NF-κB." (PMID 39456521, 2024). "A stimulated inflammatory response was found in patients with heart failure and preserved ejection fraction (HFpEF), as characterized by an increase of inflammatory molecules including TNF-alpha." (PMID 38997754, 2024). "It has been reported that patients with heart failure, some of whom have dilated cardiomyopathy, have high plasma TNF-α levels." (PMID 39365793, 2024). "It is firmly established that patients experiencing the onset of heart failure (HF) exhibit elevated concentrations of TNF-α in their bloodstream." (PMID 38542544, 2024). "Many of the involved inflammatory markers, such as IL-6, CRP, TNF-α, IL-1β, and macrophage inhibitory factor (MIF), have been associated with post-MI hypertrophy, remodeling, persistent systolic dysfunction, heart failure, and mortality." (PMID 38558749, 2024). "Physical exercise training in patients with heart failure was reported to reduce IL-6 and TNFα levels and improve functional status." (PMID 38256155, 2024). "Dapagliflozin improves diabetes-induced heart failure in diabetics by increasing epicardial fatty tissue and decreasing TNF levels." (PMID 37047011, 2023). "TNF-α level was closely related to the progression of myocardial ischemic injury, myocardial ischemia/reperfusion, myocardial remodeling and heart failure." (PMID 37175097, 2023).
heart failure (continued). "Recent studies have found that treatment with Ginaton alleviated renal interstitial fibrosis through the TGF-β pathway and that Ginaton also reduced TNF-α, IL-1β, and 5-hydroxytryptamine levels in the hippocampus of mice with heart failure." (PMID 36992835, 2023). "The contribution of inflammatory mediators such as tumor necrosis factor-α, interleukin-6, monocyte chemoattractant protein-1, nuclear factor kappa B, and oxidative injury in heart failure, which also leads to renal damage." (PMID 37691634, 2023). "For example, in heart failure (HF) induced by myocardial infarction (MI), it is possible to observe an increase in interleukin 1 beta (IL-1β), tumor necrosis factor alpha (TNF-α), interleukin 6 (IL-6), and lectin 3 levels." (PMID 36831272, 2023). "Second, we lack data on other biomarkers of inflammation such as ILs and tumor necrosis factor, which correlate with vitamin D status in studies of healthy adolescents or patients with heart failure." (PMID 36789936, 2023). "These experimental data address the clinical failure of TNF-α inhibitors in heart failure patients and further suggest targeting TNFR2 over TNF-α." (PMID 37534280, 2023). "However, enthusiasm for use of TNF-α inhibitors for treatment of patients with cardiovascular risk remains controversial as a few large multi-center comparative studies fail to demonstrate benefit for cardiovascular-related events, heart failure, death risk and improved cardiovascular outcomes." (PMID 37534280, 2023). "Tumor necrosis factor (TNF) and IL-6 are well known serum biomarkers of heart failure, along with IL-1β, but IL-1β is better as a tissue biomarker rather than a serum biomarker, as its sera levels are low." (PMID 36937911, 2023). "Some researchers concluded that even a small concentration of lipopolysaccharide can effectively induce the release of TNFα in an in vitro whole blood model of heart failure patients." (PMID 36859608, 2023). "The effects of TNF-α on the pathological remodeling and proinflammatory responses in heart failure are complex and highly receptor-specific." (PMID 36713834, 2023). "When modeled as a continuous variable, 1 log unit increase of TNF-α, KIM-1, troponin, and galectin-3 was associated with higher risk of all-cause mortality, cardiovascular death, or subsequent heart failure hospitalization in univariable analysis." (PMID 36896709, 2023). "Conversely, although some experts have advocated TNF-α antagonists (such as infliximab) for ICI-associated myocarditis, concerns have been raised regarding their application in patients with heart failure." (PMID 37876928, 2023). "Patients with heart failure, who had higher levels of TNF-α, were found to have a lower survival rate." (PMID 37887854, 2023). "Compared to the sham group, the model group exhibited a significant increase in the levels of heart failure biomarker NT-proBNP, as well as the pro-inflammatory cytokines TNF-α and IL-1β." (PMID 38138606, 2023). "Cytokines, TNF-α, IL-1β, and IL-6, were found to be elevated in patients with heart failure, and their higher levels appear to be directly related to LVEF dysfunction." (PMID 35997998, 2023). "Anti-TNF-α therapy with etanercept was also able to improve endothelial function in patients with RA and advanced heart failure." (PMID 35206342, 2022). "TNF-α has been demonstrated to induce heart failure, pulmonary edoema, and cardiomyopathy in people with advanced heart failure when it is elevated in the bloodstream." (PMID 35813433, 2022). "The hawthorn treatment group reduced the levels of IL-6, IL-8, IL-1β and TNF-α in cardiomyocytes due to doxorubicin treatment for heart failure (p < 0.01)." (PMID 36140986, 2022).
heart failure (continued). "Based on these findings, several TNF-α antibodies were initiated in clinical trials as treatments for patients with heart failure." (PMID 35844550, 2022). "TNF-α is the most studied pro-inflammatory cytokine both in experimental models of heart failure and in the course of the natural disease." (PMID 35878343, 2022). "Of note, serum TNF-α is chronically elevated in heart failure patients, pointing toward a crucial role of pro-inflammatory cytokines in general and TNF-α in particular in the onset and progression of secondary vascular inflammation and PH development." (PMID 35250621, 2022). "Another animal study revealed that nCGA protects cardiomyocytes from TNF-α–induced injury via inhibition of NF-κB signals, providing a novel therapeutic alternative for the prevention and treatment of heart failure." (PMID 35893859, 2022). "In cardiovascular diseases, the production of various inflammatory cytokines, including TNF-α, IL-1β, and IL-6, leads to tissue damage, promoting atherosclerotic plaque formation, reduced vascular function, and progression of heart failure." (PMID 35431967, 2022). "TNFα is a pro-inflammatory cytokine that is produced and secreted by cardiac myocytes in response to ischemic cardiac injury, cardiac hypertrophy, and heart failure." (PMID 35883637, 2022). "We previously reported that TACE-mediated production of TNF-α in the hypothalamic paraventricular nucleus (PVN) contributes to sympathetic excitation in heart failure (HF)." (PMID 36439267, 2022). "In all patients with available echocardiographic data, the EF was significantly lower than 50%, and these patients should be classified as having moderate-to-severe heart failure, but anti-TNF-therapy was still adopted." (PMID 35844550, 2022). "Coronary heart disease and heart failure significantly increase the production of potent inflammatory cytokines (interleukin-1—IL-1; interleukin-6—IL-6; tumor necrosis factor-α—TNF-α) in the heart and other organs." (PMID 36430892, 2022). "In our previous study, we have found increased TNF expression along with active necroptosis in post‐infarction heart failure, and thereby supporting a link between this cytokine and this necrosis‐like cell death programme." (PMID 35393789, 2022). "Excessive concentrations of TNF-α in the bloodstream will lead to left ventricular dysfunction, cardiomyopathy, and heart failure." (PMID 36035865, 2022). "In rats with heart failure, IL-10 therapy significantly improved post-MI left ventricular function by reducing IL-6 and TNF-α, whilst in ischemia-reperfusion injury, IL-10 therapy reduced inflammation and cardiomyocyte death." (PMID 36140236, 2022). "The first evidence of inflammation in HFpEF came from the observation that heart failure patients have higher levels of circulating inflammatory cytokines such as TNF-α, IL-1, IL-6, IL-8, and monocyte chemotactic protein (MCP)-1." (PMID 36672578, 2022). "There are multiple mechanisms put forward for an explanation of the increase in TNF‐α in heart failure." (PMID 35938295, 2022). "The specificity of the biosensor prepared was studied using other biomarkers of heart failure, such as TNF-α and NT-proBNP." (PMID 36557534, 2022). "A growing body of evidence shows that neurohormones and cytokines, including IL-6 and TNF-alpha, contribute to the progression of heart failure." (PMID 35847039, 2022). "Some research reports that some proinflammatory cytokines, including TNF-α and interleukin-6 are increased in hypertensive patients with heart failure." (PMID 35721105, 2022). "Elevated IL-6 and TNF-α in plasma were associated with disease severity of HCM and even heart failure with preserved ejection fraction (HFpEF)." (PMID 36267414, 2022). "On the other hand, TNF-α inhibitors are contraindicated in patients with moderate-to-severe heart failure." (PMID 35844550, 2022).
heart failure (continued). "We sought to measure the levels of adipokines, TNF-α and soluble receptors (sTNFr1, sTNFr2) in heart failure patients with reduced ejection fraction (HFrEF) due to non-ischemic cardiomyopathy (nDCM)." (PMID 36428528, 2022). "Elevated levels of tumor necrosis factor alpha (TNF-alpha), interleukin (IL)-6, and IL-1 have been found in heart failure patients and are linked with a poorer prognosis and outcomes." (PMID 36017290, 2022). "In the event of worsening or newly diagnosed heart failure, biologic therapy with TNF-alpha inhibitors should be stopped and alternative biologic agents should be taken into consideration." (PMID 35741329, 2022). "Previous efforts to treat heart failure with anti -TNF therapeutics have shown mixed outcome in animal and mouse model." (PMID 35371099, 2022). "Circulating levels of cytokines: IL-1β, TNFα, IL-10, IL6, IL-8 and IL-12 were determined and investigated regarding their association with hemodynamic parameters, clinical signs of heart failure and outcome." (PMID 36014020, 2022). "TNF-α is one of the oldest cytokines described in heart failure, and two classic large trials of anti-TNF-α therapy have been performed in heart failure patients." (PMID 36672578, 2022). "Evidence from prior research suggests that TNF-α and IL-6 levels serve as predictors of death in heart failure patients." (PMID 36547425, 2022). "and anti-TNF-α treatment reduces the abnormally elevated sympathetic nerve activity in an ischaemia-induced model of heart failure in rats." (PMID 35309046, 2022). "In fact, increased levels of Interleukins (IL), such as IL-1 and IL-6, as well as tumor necrosis factor α (TNFα), are correlated with the severity of heart failure." (PMID 35897650, 2022). "Myocardial infarction can lead to the generation of TNF-α in myocardium, and TNF-α can induce cytotoxic effect in cells, and induce cardiac insufficiency and ventricular remodeling." (PMID 35282820, 2022). "The pro-inflammatory cytokines TNFα, IL-1β and IL-6 are all involved in the inflammatory response related to the pathogenesis of heart failure." (PMID 36278179, 2022). "Clinical trials targeting TNF-α using etanercept or infliximab in heart failure (e.g., RENAISSANCE, RECOVER, RENEWAL and ATTACH) were prematurely terminated due to the lack of beneficial outcomes or, in some instances, worse outcomes for patients." (PMID 35309046, 2022). "Myopericarditis has also been attributed to treatment with mesalamine and heart failure to tumor necrosis factor inhibitor (TNFi) use." (PMID 35399407, 2022). "A growing body of evidence showed that neurohormones and cytokines, including IL-6 and TNF-alpha, contribute to the progression of heart failure." (PMID 35847039, 2022). "The evidence to date indicates that pro-inflammatory mediators like TNF-α, interleukins, reactive oxygen species and angiotensin II are increased in heart failure." (PMID 35309046, 2022). "In patients with moderate–severe CD with high disease severity, who have relative or absolute contraindications to anti-TNF drugs (e.g., demyelinating diseases, heart failure, multiple serious infections), we prefer UST monotherapy as first-line therapy." (PMID 35160280, 2022). "At the end of the 20th century, the plasma level of TNF-α was found to be elevated in patients with heart failure, and TNF-α contributed to systolic dysfunction, hypertrophy, and myocardial apoptosis in the failing heart." (PMID 35844550, 2022). "TNF-alpha levels are elevated in patients diagnosed with heart failure due possibly due to an increase in ventricular wall stress." (PMID 35915691, 2022). "AD progression is directly correlated with TNFα production in In ApoE-/-, and in clinical studies, circulating levels of TNFα and soluble TNFRs are independent predictors of mortality in patients with heart failure." (PMID 33626069, 2021).
heart failure (continued). "Alternatively, it is possible that those with rec-AN have a more optimal dietary pattern as a result of their eating disorder; findings from a study in patients with heart failure found lower TNF-α levels in patients with diets lower in saturated fats." (PMID 34442458, 2021). "Previous studies have shown that vitamin D3 supplementation in older adults with chronic inflammatory diseases such as osteoarthritis and heart failure significantly decreases the levels inflammatory mediators such as TNFα in the circulation." (PMID 36284901, 2021). "The significant role of inflammation in the pathophysiological processes of various heart diseases has been attracting attention since elevated levels of tumor necrosis factor (TNF) were reported in patients with heart failure for the first time in 1990." (PMID 34072423, 2021). "In an experimental heart failure model, in vivo TNFα inhibition reduced cardiac mitochondrial dysfunction, oxidative stress, and apoptosis." (PMID 34966735, 2021). "As far as heart failure is concerned, TNF inhibitor treatment can protect the heart by controlling inflammation." (PMID 35187113, 2021). "The increased expression of ADAM17, TNFα, and sIL-6R has a vital implication in aggravating cardiac dysfunction during heart failure development." (PMID 34966735, 2021). "Patients with cardiomyopathy, heart failure, or other atherosclerotic lesions also exhibited elevated TNF-α levels." (PMID 34576032, 2021). "Studies have also shown that HIF-1α is responsible for recruiting M1 macrophages that release TNF-α in patients with heart failure." (PMID 34497517, 2021). "Recent studies focused their attention on the role of the proinflammatory cytokine tumor necrosis factor in heart failure development, showing a direct relationship between the level of TNFα expression and the severity of heart disease." (PMID 33667229, 2021). "On the contrary, adverse effects of the anti-TNF-α antibody Infliximab have been described in patients with heart failure (HF)." (PMID 33881711, 2021). "The use of infliximab, a monoclonal antibody against tumor necrosis factor (TNF)-α, should be avoided in patients with decreased LVEF or symptomatic heart failure because of the risk of worsening heart failure." (PMID 33997442, 2021). "It should be noted that the immunomodulatory effect of TNF-α in heart failure is not well understood, mostly because of its involvement in the activation of endothelial cells and pro-inflammatory role during the early inflammatory phase." (PMID 33053859, 2020). "Ishikawa, Kobayashi, Sugiyama, Onoda and Ishimitsu, 2013 are in agreement with our study where they showed that TOL decrease the expression of both TNF‐α and NF‐κB in rat model of heart failure." (PMID 32996719, 2020). "Although epidemiologically, TNF levels are predictive of heart failure mortality, a clinical trial in heart failure patients observed a higher hospitalization rate in the group receiving 10 mg/kg infliximab (anti-TNF) compared with the placebo group." (PMID 32805626, 2020). "Next to inflammatory diseases, where anti-TNF therapy is approved, increased levels of TNF are found in several degenerative diseases, such as heart failure (HF) or neurodegenerative diseases." (PMID 32528961, 2020). "Proinflammatory cytokine levels, such as tumor necrosis factor-alpha (TNF-α) and IL-6, are closely associated with the heart failure status, suggesting that inflammatory cytokine signaling contributes to progressive pump failure." (PMID 32664594, 2020). "Preclinical data in models of heart failure suggested that TNF neutralization in HF would be beneficial." (PMID 32528961, 2020). "Results of anti-TNF-α treatments in patients with heart failure or with autoimmune inflammatory diseases demonstrated the relevance and a dual role of TNF-α in cardiovascular diseases in humans." (PMID 33053859, 2020).